ARG2 (arginase 2)
Diseases named in the same sentence as ARG2 in open-access papers (continued):
Sharing a sentence is not in itself a finding about the gene and the disease.
cancer (54 papers, 2008 to 2026). A tumor composed of atypical neoplastic, often pleomorphic cells that invade other tissues. "In recent years, both ARG1 and ARG2 have been linked to many diseases, such as inflammatory, cardiovascular, and neurodegenerative diseases, as well as various cancers, as described in detail in this review." (PMID 39337272, 2024). "Researchers have reported that upregulated Arg2 expression is implicated in tumors with high grade and patient prognosis prediction and that the suppression of arginase inhibits cancer cell growth." (PMID 36604146, 2022). "Recently, the mitochondrial ARG2 has been implicated in metabolic processes, which allow both cancer and suppressive immune cells to function." (PMID 36010962, 2022). "In this study, we developed a prediction model for the “inflammation-cancer transition” using six predictors: ARG2, HSP90AA1, EZH2, ICAM1, macrophage M1, and activated CD4 memory T cells." (PMID 40352921, 2025). "The prediction model for the “inflammation-cancer transition,” developed using the experimental cohort, demonstrated the highest weight ratio for ARG2, aligning with the findings from the training cohort." (PMID 40352921, 2025). "Arginine levels have also shown to be correlated with ICI response in other cancers, and arginase 2 has been shown to downregulate macrophage-mediated inflammation via IL-1067,68." (PMID 38429349, 2024). "The significance of ARG2 is fundamental not only for cancers but also for inflammation, especially for macrophage function." (PMID 39337272, 2024). "The same group developed a study using 34 peptides covering the entire ARG2 sequence and assessed the reactivity of these peptides in peripheral blood mononuclear cells (PBMCs) obtained from healthy donors and cancer patients." (PMID 39337272, 2024). "The anti-cancer function of CD8+ T cells with Arg2 knockout is related to enhanced cytotoxicity, memory formation, and the persistence of anti-cancer CD8+ T cell responses." (PMID 39337272, 2024). "The overexpression of ARG1 and ARG2 in cancer impairs T cell function involving L-arginine, which is necessary for T cell differentiation and proliferation." (PMID 39337272, 2024). "Cancer cell growth is markedly reduced when ARG2 expression is knocked down in basal-like breast cancer." (PMID 37108109, 2023). "Ornithine is synthesized in cancer cells by arginase 2 (ARG2) during S/G2/M phases only, and by the ornithine aminotransferase (OAT) in normal cells." (PMID 37108109, 2023). "We found that cytotoxic ARG2-specific CD8+ T cells can specifically recognize ARG2-expressing activated Tregs along with ARG2-expressing cancer cell lines, highlighting the anti-regulatory function of these effector T cells." (PMID 36175673, 2023). "Arginase biology has been studied in multiple contexts, resulting in the identification of ARG1 and ARG2 as therapeutic targets in cancer, as well as potential biomarkers for cancer progression." (PMID 36010962, 2022). "The relevance of ARG1 and ARG2 in cancer, documented by many research groups, has prompted a search for pharmaceutical inhibitors of these enzymes in order to alter the outcome of the immune response and develop new treatment options." (PMID 36010962, 2022). "Along with the previously validated role of ARG1 in cancer, the particular significance of ARG2 as a therapeutic target has emerged as its levels correlate with malignant phenotype and poor prognosis." (PMID 36010962, 2022). "Over-expression of ARG1 or ARG2 disrupts L-arginine homeostasis which leads to metabolic disorder-related diseases, Alzheimer’s disease (AD), cancer, etc." (PMID 36014374, 2022). "This latter pattern of expression, in contrast to cancer-cell ARG2 expression, was significantly related to an advanced stage and poor prognosis, independently of the stage of the disease." (PMID 34344457, 2021). "A relationship has been established between ARG2 expression and cancer in various organs, including the thyroid." (PMID 34748583, 2021).
cancer (continued). "ARG2 was expressed mainly by cancer-associated fibroblasts (CAFs) (58/98 cases; 59.2%), while ASS1 by cancer cells (75/98 cases; 76.5%)." (PMID 34344457, 2021). "In the remaining 25 cases, ARG2 was strongly expressed in the cytoplasm of 10–90% of the cancer cell population (median 40)." (PMID 34344457, 2021). "The results showed that levels of most of the immunosuppressive cytokines, such as Arg2, CCL28, DNMT1, and EZH2, were upregulated in the high-risk subtype, suggesting that high-risk A-HCC patients have reduced cancer-immunity cycle activity." (PMID 34512165, 2021). "Of interest, ARG2 expression by cancer cells and by CAFs was inversely inter-related (p = 0.001, r = 0.32)." (PMID 34344457, 2021). "ARG2 was expressed by cancer cells in one-fourth of tumors examined, but this expression was not related to stage, histology, or prognosis of patients." (PMID 34344457, 2021). "Cancer cells exclusively use arginase 2 (ARG2) to synthesize ornithine, whereas normal epithelial cells depend on ornithine aminotransferase (OAT)." (PMID 32296576, 2020). "Another arginase isoform—ARG2—is also revealed to be dysregulated in cancers and play different roles in different tissues and organs." (PMID 30320132, 2018). "Since ARG2-expressing CAFs were present within and around necrotic areas, we next examined the relationship between ARG2 expression and hypoxia in cancer tissue using double immunostaining." (PMID 23424623, 2013). "Thus, L-arginine metabolism via ARG-2 is an immunoregulatory pathway used by Tregs in human tissues, with significant implications for both autoimmunity and cancer." (PMID 39861764, 2025). "Accumulating evidence has highlighted the essential role of ARG2 in the regulation of cancer progression, suggesting that the inhibition of ARG2 may lead to clinical benefits for patients with cancer." (PMID 39337272, 2024). "Additionally, this is the first study to confirm the benefits of ARG2 inhibition in cancer treatment." (PMID 39337272, 2024). "This is the first study validating the benefits of pharmacological inhibition of ARG2 in cancer." (PMID 36010962, 2022). "The most marked cancer-related difference seems to be associated with ODC and ARG2 expression patterns, mostly changed from very strong to strong (with DDAHs) or moderate (with PRMTs), and with loosening of ASS1 and ASL association with each other as well as other pathway enzymes." (PMID 34439753, 2021). "Knockdown of ARG2 in BLBC markedly reduces cancer cell growth and causes G2/M arrest but does not prompt compensation via OAT60." (PMID 32296576, 2020). "Likewise, ARG2 is expressed at high levels in solid as well as liquid malignancies (Cancer Cell Line Encyclopedia; Part C in S1 Fig)." (PMID 30307989, 2018). "Hence, this suppressive activity of MDSCs against T cells is partly mediated by Arg2, which unravels an attractive therapeutic target against cancer." (PMID 28191010, 2017). "The high expression of ARG2, FGFBP1 and FOXM1, are associated with several cancers." (PMID 24481205, 2013). "The second isoform, Arg2, is located in mitochondria and absent from the urea cycle and has been implicated in the mediation of endothelial cell senescence, smooth cell apoptosis, macrophage proinflammatory responses and cancer cell growth." (PMID 36604146, 2022). "However, another study showed that ARG2 has a cancer suppressor effect." (PMID 34975331, 2022). "Neither ASS1 nor ARG2 expression by cancer cells was linked with TIL-score or PD-L1 expression." (PMID 34344457, 2021). "In this latter case, ARG2 inhibitors could sustain a high intratumoral arginine content and, eventually, reverse the immunologically cold microenvironment, by allowing colonization by anti-cancer TILs." (PMID 34344457, 2021). "This is the case of arginine, which is converted into ornithine and urea by the enzymes arginase 1 (ARG1) and arginase 2 (ARG2), expressed by several cancer cells, as well as by MDSCs and TAMs." (PMID 41368640, 2025).
cancer (continued). "In contrast, ginsenoside Rg1 downregulated the mRNA expression of ARG2, MMP1, S100A4, and RAPSN, and upregulated the mRNA expression of LAMC2, DSC2, KRT6A, and FOSB, thereby enhancing the anti-cancer function of granulocytes inhibited by NA." (PMID 36817446, 2023). "The immunosuppressive mechanism of NA can be described as follows: NA elevated the mRNA expression of ARG2, MMP1, S100A4, and RAPSN in granulocytes, thereby inhibiting the CKA of granulocytes and promoting cancer development." (PMID 36817446, 2023). "Transcriptome sequencing analysis and qRT-PCR showed that NA elevated the mRNA expression of ARG2, MMP1, S100A4, and RAPSN in granulocytes, thereby reducing the anti-cancer function of granulocytes." (PMID 36817446, 2023). "The activity of arginase enzymes (ARG1 and ARG2), which catalyze L-arginine into ornithine and urea, is increased in the TME of multiple cancers including breast cancer." (PMID 33747948, 2021). "Cancers with CD38-, ARG2- expression patterns, corresponding to an undifferentiated state, had significantly lower 10-year recurrence-free survival compared to the most differentiated group (CD38+ARG2+)." (PMID 29464091, 2018). "The level of ARG2 protein increases as the disease progresses from CIN III to CC, supporting the view that ARG2 mRNA expression is significantly upregulated in women with cancer lesions." (PMID 40352921, 2025). "The two arginase isoforms, arginase 1 (ARG1) and arginase 2 (ARG2), regulate the proliferation of cancer cells, migration, and apoptosis; affect immunosuppression; and promote the synthesis of polyamines, leading to the development of cancer." (PMID 39337272, 2024). "ARG2, depending on the access of L-arginine, is also able to regulate CD8+ T cells, influencing their functions of memory formation for self-renewal and transformation into effector T cells and regulating their anti-cancer function." (PMID 39337272, 2024). "Indeed, this antagonistic interplay between ARG2-expressing CAFs and TILs resulted in poor prognosis in the current series of patients, despite the arginine synthetic activity of ASS1 expressing cancer cells." (PMID 34344457, 2021). "Moreover, another important drawback is that functional analysis of the enzymes expressed in cancer cells and fibroblasts is certainly necessary to strengthen the ASS1/ARG2-based grouping of lung tumors." (PMID 34344457, 2021). "Patients with ASS1 expression by cancer cells had a better prognosis especially when CAFs did not express ARG2 (p = 0.004)." (PMID 34344457, 2021). "ARG2 and ASS1 enzymes are extensively expressed in NSCLC stroma and cancer cells, respectively." (PMID 34344457, 2021). "Bivariate stratification, however, showed that patients with ASS1 expression by cancer cells had a better prognosis especially when CAFs did not express ARG2 (p = 0.004)." (PMID 34344457, 2021). "The expression of ARG2, but not ARG1, has been shown to be upregulated by hypoxia and implicated in mediating hypoxia-induced cancer cell proliferation." (PMID 32872669, 2020). "Moreover, Wu at al. analyzed the Cancer RNA-seq Nexus (CRN) public database and found ARG2 to be upregulated in CRC tumors." (PMID 32932854, 2020). "In addition, the local expression of key pathway enzymes (ARG1, ARG2, DDAH1, DDAH2, NOS2, ODC1, PRMT1, and PRMT5), as potential therapeutic targets, was evaluated in reference to cancer pathology." (PMID 32872669, 2020). "Because of its high and specific expression in leukemic but not normal progenitors, frequent involvement in cancers and the availability of small molecule inhibitors, ARG2 was deemed to be a promising therapeutic target." (PMID 30307989, 2018). "The proliferation of cancer cells was not significantly affected by ARG2 induced by hypoxia, and oxidative stress-induced apoptosis of cancer cells but CAFs themselves was not prevented by polyamine produced by ARG2 in response to hypoxia." (PMID 23424623, 2013).
cancer (continued). "ARG2 expression in cancer cells was not restricted to areas around necrosis or near CAIX-, SLC2A1-, or HIF-1α-expressing cells (data not shown)." (PMID 23424623, 2013). "Out of 98 cases, in 73 (72.5%) there was no ARG2 or sporadic cell expression in cancer cells." (PMID 34344457, 2021). "ASS1 and ARG2 expression by cancer cells or by CAFs were not related to the expression of HIF1α, LDH5, or CA9 by cancer cells." (PMID 34344457, 2021).
infection (35 papers, 2011 to 2025). The state of being infected such as from the introduction of a foreign agent such as serum, vaccine, antigenic substance or organism. "Whether the increased expression of Arg2, Nos2, SpmS, and Mcp-1 in putrescine supplementation in infected macrophages is associated with macrophage polarization during infection warrants further investigation." (PMID 37000792, 2023). "The ARG2 inhibition restored T-cell immunity against secondary infection in septic immunosuppressed hosts." (PMID 40860137, 2025). "Expression of genes such as Il17 and Cxcl1 was 5–10-fold lower after infection with Salmonella and C. albicans than infection with Salmonella alone, with an increase in arginase II (Arg2) expression." (PMID 40903573, 2025). "Utilizing a “two-hit” mouse model, we demonstrated that pharmacological blockade and in vivo knockdown of ARG2 enhanced T cell immune responses against secondary infections by restoring CD4+ T cells, reducing bacterial loads and improving survival rates." (PMID 40860137, 2025). "In spring, infection induced upregulation of inos at 24 hpi, while upregulated expression of il-12p35, ifn-γ2, arginase 2 and il-10 was observed only in the spring both at 24 and 96 hpi." (PMID 38157099, 2024). "In newborn mice, the abundance of CD71+ erythroid cells inhibited the immune response of T-cells to infection through the expression of arginase-2, effectively mitigating excessive inflammatory responses when faced with infection." (PMID 39000360, 2024). "In line with an earlier report, we found that the expressions of both types of arginase, Arg-1 and Arg-2, in the murine spleen were increased by STm infection." (PMID 39102375, 2024). "Infection with H. pylori leads to an upregulation in the expression of ARG2, resulting in decreased inflammatory cytokine expression and the inhibition of M1 macrophage activation." (PMID 38730482, 2024). "arg2:GFP-positive neutrophils were present in the vicinity of Mm infection, with both infected and uninfected neutrophils expressing arg2:GFP." (PMID 37078586, 2023). "We observed macrophages expressing arg2:GFP during infection and at wound-healing stages of tailfin transection." (PMID 37078586, 2023). "arg2:GFP expression was assessed at a later stage of Mm infection (4 dpi), a stage at which innate immune granulomas are forming and when it is likely that leukocyte phenotypes are more diverse and polarised owing to immune modulation by mycobacteria." (PMID 37078586, 2023). "Characterising the macrophage polarisation infection response fully will require further study, for which the arg2:GFP zebrafish line will be an important tool." (PMID 37078586, 2023). "The arg2:GFP line is an exciting addition to the zebrafish transgenic toolbox with which to investigate innate immunity during infections." (PMID 37078586, 2023). "We identify a small population of macrophages that express arg2 after injury and infection, suggesting the presence of anti-inflammatory macrophages in zebrafish." (PMID 37078586, 2023). "We assessed the early response to Mm infection at 1 dpi and found that a subpopulation of neutrophils express arg2:GFP early in infection." (PMID 37078586, 2023). "Following a range of immune challenges, including tailfin transection (sterile injury) and Mycobacterium marinum (bacterial) and Cryptococcus neoformans/Candida albicans (fungal) infections, arg2:GFP expression was predominantly upregulated in neutrophils." (PMID 37078586, 2023). "The mitochondrial isoform of Arginase (Arg2) is also slightly regulated by infection with L. amazonensis at 4–24 h and LPS stimulation at 4 and 24 h." (PMID 35202090, 2022). "In the present study, four host genes (Gm15587, Nos2, Pycr1, Arg2) were enriched in this metabolic pathway, two of which (Nos2, Pycr1) were downregulated in the infection group." (PMID 32509459, 2020).